TRAF2 (TNF receptor associated factor 2)
Diseases named in the same sentence as TRAF2 in open-access papers (continued):
Sharing a sentence is not in itself a finding about the gene and the disease.
nasopharyngeal carcinoma (5 papers, 2012 to 2024). A carcinoma arising from the nasopharyngeal epithelium. "Some studies reported that TRAF2 was involved in EBV-associated nasopharyngeal carcinoma development." (PMID 32566659, 2020). "In nasopharyngeal carcinoma cells, overexpression of TRAF2 promotes cancer cell proliferation and anchorage-independent growth." (PMID 36012427, 2022). "All these results demonstrated that TRAF2 had a crucial role in nasopharyngeal carcinoma development." (PMID 32566659, 2020). "However, the expression of TRAF2 and its role in nasopharyngeal carcinoma are less known." (PMID 32566659, 2020). "In the present study, we found that TRAF2 was overexpressed in nasopharyngeal carcinoma (NPC) cells." (PMID 32566659, 2020). "In addition, Zhu and colleagues found that TRAF2 expression significantly increased in nasopharyngeal carcinoma (NPC) cells." (PMID 39061149, 2024). "Our findings are the first description of LMP2A alteration of LMP1 signaling by TRAF2 modulation in an animal model, and support similar findings in EBV-positive nasopharyngeal carcinoma and Burkitt's lymphoma cell lines." (PMID 22536156, 2012).
Stroke (5 papers, 2019 to 2023). Sudden impairment of blood flow to a part of the brain due to occlusion or rupture of an artery to the brain. "SNHG15, which is an IL-4-induced lncRNA in macrophages, uniquely represses K63-linked ubiquitination of TRAF2 to promote M2 macrophage polarization and thereby attenuates inflammatory responses after stroke." (PMID 34980176, 2022). "In addition, SNHG15 is an IL-4-induced macrophage LncRNA that uniquely inhibits K63 linked TRAF2 ubiquitination, thereby promoting M2 macrophage polarization and alleviating inflammatory response after stroke." (PMID 37153000, 2023). "Our results also showed that TRAF2 formed more complex with MLKL following experimental stroke, suggesting that TRAF2 may inhibit necroptosis by abating the association between MLKL and RIP3." (PMID 30988281, 2019). "We found that stroke work is significantly lower in the in the TRAF2 mice, perhaps indicating a diminished cardiac function." (PMID 37229235, 2023). "The immunohistochemical experiment was performed to determine the expression of RIG-I, Traf2 and NF-κB (p65) in vascular endothelium after stroke." (PMID 34462642, 2021). "In this study, we investigated the role of TRAF2 in experimental stroke using a mouse middle cerebral artery occlusion (MCAO) model and in vitro cellular models." (PMID 30988281, 2019). "Gene knockdown of TRAF2 by lentivirus was utilized to investigate the role of TRAF2 in stroke outcomes." (PMID 30988281, 2019). "Since nec-1 is a specific necroptosis inhibitor, these results demonstrate that TRAF2 plays a protective role by inhibiting necroptotic cell death following experimental stroke." (PMID 30988281, 2019). "In conclusion, our study showed that TRAF2 was induced in the brain following experimental stroke." (PMID 30988281, 2019). "As we showed, neurons are one of the sources for TRAF2 induction following experimental stroke." (PMID 30988281, 2019). "Also, stroke work was significantly lower in the TRAF2 mice when compared to CTR mice." (PMID 37229235, 2023).
acute myeloid leukemia (4 papers, 2016 to 2025). Acute myeloid leukemia (AML) is a group of neoplasms arising from precursor cells committed to the myeloid cell-line differentiation. "DFRP1 is also overexpressed in acute myeloid leukaemia (AML) and interacts with TRAF2." (PMID 34664086, 2021).
B cell lymphoma (4 papers, 2018 to 2023). "Taken together, we suggest that IAP antagonist plus chemotherapeutics may be more effective in treating TRAF2 or TRAF3 deficient B cell lymphomas." (PMID 37679334, 2023). "Genetic alterations of TRAF2 or TRAF3 are observed in subsets of human B-cell lymphomas and B cell-specific deletion of TRAF3 led to lymphoma development in aged mice." (PMID 37679334, 2023). "Our studies provide insight into mechanisms regulating DNA damage-induced apoptosis in B cells and may help develop effective therapies for TRAF2/3 mutant B-cell lymphomas using IAP antagonist." (PMID 37679334, 2023). "Our studies provide insight into mechanisms modulating DNA damage-induced apoptosis and may help to develop more effective treatment for TRAF2 or TRAF3 mutant B-cell lymphomas using IAP antagonists." (PMID 37679334, 2023). "Assuming that in humans TRAF2 and TRAF3 mutations occur in premalignant cells, they may contribute to the initiation of B cell lymphomas through a similar RelB-dependent mechanism as we describe here for LMP1/CD40 mice." (PMID 36110848, 2022). "In accordance with the notion that the alternative NFκB pathway and therefore also TRAF2 and TRAF3 act as tumor suppressors in B-cells, mice with B-cells deficient in TRAF3 expression demonstrate prolonged B-cell survival and develop spontaneous B-cell lymphoma at a higher age." (PMID 36011046, 2022). "TRAF2 deficiency in B cells also resulted in elevated NF-κB2 activation; however, TRAF2 and TRAF3 may play opposite roles in regulating NF-κB1 activation that is important for human B cell lymphoma survival and proliferation." (PMID 37679334, 2023).
bladder cancer (4 papers, 2018 to 2025). "BRCC3 exerts its oncogenic role via binding to TRAF2, which in turn leads the activation of NF-κB signaling in bladder cancer." (PMID 34604222, 2021). "Our results indicate that high BRCC3 expression activates NF-κB signaling by targeting TRAF2 for activation, which in turn facilitates tumorigenesis in bladder cancer." (PMID 34604222, 2021). "Our study provides novel insight into the function of BRCC3 in the TRAF2-activating NF-κB signaling cascade in bladder cancer." (PMID 34604222, 2021). "We demonstrated that BRCC3 facilitates tumorigenesis via TRAF2 in bladder cancer." (PMID 34604222, 2021). "For instance, in bladder cancer, BRCC36 enhances NF-κB pathway activation and drives inflammation and oncogenesis by directly interacting with TRAF2." (PMID 41463377, 2025).
cardiac hypertrophy (4 papers, 2014 to 2022). "For example, previous research has found that overexpressed cardiac-specific Traf2 enhances cardiac hypertrophy by activating AKT/GSK3β signaling pathway." (PMID 31998553, 2020). "Transgenic mice overexpressing TRAF2 driven by MHC promoter (MHC-TRAF2HC demonstrated the symptoms of progressive cardiac hypertrophy with increased myocardial fibrosis even after 12 weeks." (PMID 30186311, 2018). "Cardiomyocyte-specific TRAF2 transgenic mice developed a time-dependent increase in cardiac hypertrophy, left ventricular (LV) dilation, and adverse LV remodeling, and a significant decrease in heart function." (PMID 24611063, 2014). "Furthermore, a recent study demonstrated that the adaptor protein TRAF2 enhanced cardiac hypertrophy and left ventricular dysfunction in mice in response to TAC." (PMID 35096272, 2022). "However, the exact contribution of NF-κB activation in the induction of cardiac hypertrophy when TRAF2 is overexpressed needs to be further verified." (PMID 30186311, 2018). "However, futuristic experimental reports will establish an exact mechanism followed by TRAF2 in regulating the development of cardiac hypertrophy." (PMID 30186311, 2018). "However, the precise contribution of TRAF2 in the development of adult mammalian cardiac hypertrophy is somewhat unclear." (PMID 30186311, 2018). "Furthermore, TRAF2 and TRAF5, possible downstream targets of TWEAK/Fn14 signaling, have been implicated in cardiac hypertrophy." (PMID 24611063, 2014). "Therefore, it may be possible that as a critical protein component of NF-κB signaling, TRAF2 modulates NF-κB signaling complex through first activating the Akt signaling that ultimately resulted in cardiac hypertrophy." (PMID 30186311, 2018). "Taken together, CD147 glycosylation mediated the binding of TRAF2 to CD147, subsequently activated downstream TAK1 signalling, and enhanced oxidative stress and ferroptosis, thereby promoting the progression of maladaptive cardiac hypertrophy." (PMID 35096272, 2022). "Akt signaling pathway is known for its role in cardiac hypertrophy, however, the exact mechanism by which TRAF2 specifically activating Akt pathway is not clear." (PMID 30186311, 2018).
inflammatory bowel disease (4 papers, 2017 to 2021). A spectrum of small and large bowel inflammatory diseases of unknown etiology. "Previous studies on inflammatory bowel disease have shown that UDCA specifically inhibits TNFα-induced IL-8 release from monocytes by inhibiting TNF receptor associated factor (TRAF2) activation." (PMID 33129276, 2020). "TRAF2-deficient mice spontaneously develop inflammatory bowel diseases, which could be a background for developing inflammation-induced cancer." (PMID 34257589, 2021). "A potential role for TRAF2 and TRAF3 in regulating human inflammatory bowel disease (IBD) is indicated by the finding that the expression level of these TRAF members is upregulated in the colonic tissue of IBD patients." (PMID 30140268, 2018).
leukemia (4 papers, 2019 to 2025). A malignant (clonal) hematologic disorder, involving hematopoietic stem cells and characterized by the presence of primitive or atypical myeloid or lymphoid cells in the bone marrow and the blood. "For chronic myelogenous leukemia (CML), it has been reported that the TRAF2-interacting TNFRSF receptor CD27 stimulates the oncogenic Wnt-β-catenin-TNIK-TCF4 pathway, resulting in enhanced proliferation of leukemia stem cells and leukemia progression in a TRAF2-dependent manner." (PMID 36011046, 2022). "After 6 hours of stimulation with IL-33, we observed significantly increased expression of Bcl-xl, TRAF-1, TRAF-2, and Mcl-1, but not Bcl-2 in leukemia cells." (PMID 30742053, 2019).
ovarian carcinoma (4 papers, 2014 to 2024). A malignant neoplasm originating from the surface ovarian epithelium. "The expression of TRAF2, 3 and cIAP1 in ovarian cancer cell lines that negatively regulate NIK expression remained comparable to control cells." (PMID 24533079, 2014).
cardiomyopathy (3 papers, 2013 to 2024). A disease of the heart muscle or myocardium proper. "TRAF2-mediated mitophagy in cardiac myocytes facilitates removal of cytosolic protein aggregates and can be stimulated to ameliorate proteotoxic cardiomyopathy." (PMID 39651239, 2024). "Fourth, attenuation of mitophagy via reduction of TRAF2 markedly accelerates development of cardiomyopathy with increased mortality in these mice." (PMID 39651239, 2024). "Furthermore, TRAF2 gain of function experiments demonstrate that stimulating mitophagy can be a translational strategy to remove protein aggregates, improve mitochondrial structure and function, and delay the development of cardiomyopathy." (PMID 39651239, 2024). "TRAF2 expression was increased in failing mouse hearts, and both TRAF2 and its direct downstream signalling partner TAK1 accelerated pressure overload-induced cardiomyopathy and oxidative stress-mediated injury." (PMID 35096272, 2022). "While we also observe increased expression and mitochondrial localization of the mitophagy mediator PARKIN, loss of PARKIN does not worsen the cardiomyopathy seen in R120G CRYAB transgenic mice, unlike the findings seen in R120G CRYAB mice with ablation of one TRAF2 allele in cardiac myocytes." (PMID 39651239, 2024).
Cerebral ischemia (3 papers, 2019 to 2025). Restriction of arterial blood supply to the brain associated with insufficient oxygenation to support the metabolic requirements of the tissue. "To investigate the molecular mechanisms underlying the protective role of TRAF2 in cerebral ischemia, we assessed the levels of RIP1, RIP3 and MLKL following MCAO." (PMID 30988281, 2019). "The mechanism underlying TRAF2 induction following cerebral ischemia needs further investigation." (PMID 30988281, 2019). "Consistently, in the in vivo mouse MCAO model, we observed that TRAF2 knockdown enhanced cerebral ischemia-induced neuroinflammation." (PMID 30988281, 2019). "We used a well-established MCAO and reperfusion injury model to examine the expression pattern of TRAF2 following cerebral ischemia." (PMID 30988281, 2019). "To conclude, TRAF2 likely serves as a suppressor for cerebral ischemia-induced necroptosis through interaction with MLKL." (PMID 30988281, 2019). "We showed that brain ischemia-induced TRAF2 was localized predominantly in neurons and microglia in the ipsilateral cortex and striatum." (PMID 30988281, 2019). "To investigate whether the post-ischemic induction of TRAF2 functioned through a neuronal mechanism to impact brain pathology following cerebral ischemia, we utilized an in vitro neuronal necroptosis model." (PMID 30988281, 2019). "We showed here that TRAF2 was induced in the brain following cerebral ischemia." (PMID 30988281, 2019). "Thus, TRAF2 induction likely inhibits cerebral ischemia-induced necroptosis through increased complex formation with MLKL, consequently inhibiting the association between MLKL and RIP3." (PMID 30988281, 2019). "However, whether TRAF2 participates in the brain pathology following cerebral ischemia remains unclear." (PMID 30988281, 2019). "To further show that TRAF2 knockdown exacerbates ischemic damage via enhanced necroptosis, we investigated whether nec-1 could rescue the cell death augmented by TRAF2 knockdown following cerebral ischemia." (PMID 30988281, 2019). "In the present study, the protein levels of IRE1α and TRAF2 were increased in the BCCAO group, which suggests that the ER stress signaling cascade was activated by brain ischemia." (PMID 38401021, 2024). "In consistent, we also did not observe the disruption of TRAF2-MLKL binding in the ipsilateral striatum following cerebral ischemia." (PMID 30988281, 2019). "Whether TRAF2 plays a protective/detrimental role in cerebral ischemia in vivo has not been investigated." (PMID 30988281, 2019).
COVID-19 (3 papers, 2020 to 2024). A disease caused by infection with severe acute respiratory syndrome coronavirus 2. "From the 44 DEPs, all of the proteins were upregulated in patients with COVID-19 compared with their DCs, except TRAF2 and IL17A." (PMID 37047248, 2023).
glioma (3 papers, 2021). A benign or malignant brain and spinal cord tumor that arises from glial cells (astrocytes, oligodendrocytes, ependymal cells). "Further, some recent studies have reported TRAF2 to be upregulated in multiple cancer types including the glioma and can serve as prognostic biomarker." (PMID 34117217, 2021). "To test whether TRAF2 can regulate the stability of EGFR in glioma cells, we performed knockdown of DYRK1A and TRAF2 in human glioma cell lines U251 and A172, and analyzed the protein level of EGFR." (PMID 34117217, 2021). "Recent studies have begun to unravel the role of TRAF2 in cancers, including in the glioma." (PMID 34117217, 2021). "Further, silencing of DYRK1A inhibits the growth of glioma cells mediated by TRAF2." (PMID 34117217, 2021). "Specifically, elevated IRE1 phosphorylation, Tumor Necrosis Factor (TNF) Receptor-Associated Factor-2 (TRAF2) expression, Apoptosis Signal-Regulating Kinase-1 (Ask1) phosphorylation, c-Jun N-Terminal Kinase (JNK) phosphorylation, and Noxa expression appeared in gefitinib-treated glioma cells." (PMID 33920356, 2021). "Silencing of DYRK1A or TRAF2 increases EGFR degradation and inhibition of the growth of glioma cells." (PMID 34708541, 2021).
ischemia (3 papers, 2019 to 2024). A hypoperfusion of the BLOOD through an organ or tissue caused by a PATHOLOGIC CONSTRICTION or obstruction of its BLOOD VESSELS, or an absence of BLOOD CIRCULATION. "In a murine ischemia/reperfusion model, cardiac-restricted overexpression of TRAF2 resulted in NF-κB activation and protection from ischemia-induced cardiomyocyte death." (PMID 35252400, 2022). "It’s shown that TRAF2 deletion inhibited cardiac ischemia-reperfusion injury in mice." (PMID 39546553, 2024). "To investigate whether post-ischemic induction of TRAF2 impacts microglial survival, we utilized an in vitro microglial necroptosis model under mimicked ischemia condition." (PMID 30988281, 2019). "Together, our results suggest that neuronal induction of TRAF2 under the ischemia-induced inflammatory condition may protect neurons against necroptosis." (PMID 30988281, 2019).
Lymphadenopathy (3 papers, 2018 to 2023). Enlargement (swelling) of a lymph node. "To test whether TRAF2/3 double deficiency enhances genomic instability in B cells, we isolated B cells from 5 diseased B-TRAF2/3-DKO mice with splenomegaly and lymphadenopathy or ascites and prepared metaphases from 5 samples." (PMID 37679334, 2023). "Similar to the Traf2fl/flMx1Cre and Traf2fl/flCd19Cre mice, mice expressing a TRAF2 dominant negative transgene (TRAF2-DN) devoid of the N-terminal RING and zinc finger domains display splenomegaly and lymphadenopathy." (PMID 30405612, 2018). "Similarly in TRAF2DN-tg mice that express a dominant negative form of TRAF2 specifically in lymphocytes (Igh-TRAF2DN), inhibition of TRAF2 also leads to splenomegaly and lymphadenopathy due to constitutive NF-κB2 activation and increased numbers of B cells." (PMID 30294322, 2018).
lymphoma (3 papers, 2022 to 2025). A malignant (clonal) proliferation of B- lymphocytes or T- lymphocytes which involves the lymph nodes, bone marrow and/or extranodal sites. "We suggest that TRAF2/3-deficient 264 C lymphoma may serve as a model for testing new IAP antagonists." (PMID 37679334, 2023). "To further test whether TRAF2 deficiency or TRAF2/3 double deficiency also render lymphoma cells more sensitive to IAP antagonist treatment, we generated TRAF2-KO Ly1 cells (Ly1-P30) and TRAF2/3-DKO Ly1 cells (Ly1-K77)." (PMID 37679334, 2023). "Further elucidating the role of TRAF2 and TRAF3 deficiency in B cell lymphomagenesis may help sensitizing these mutant lymphomas to chemotherapeutic drugs or other therapeutics." (PMID 37679334, 2023). "Likewise, transgenic mice expressing Bcl2 and a RING/Zn finger domain-deletion mutant of TRAF2 develop lymphoma with high frequency." (PMID 36011046, 2022). "Overall, we suggest that deficiency in TRAF2 or TRAF3 may confer survival advantage to B cells via elevated NF-κB2 that predisposes B cells to lymphomagenesis by permitting them to accumulate low frequency genetic alterations, other than chromosomal translocations, that eventually cause lymphoma." (PMID 37679334, 2023). "Our data showed that TRAF2-KO, TRAF3-KO, and TRAF2/3-DKO lymphoma cells were more sensitive to AZD treatment alone or to combined treatment of AZD/DOX." (PMID 37679334, 2023). "We treated Ly1 parental (Ly1-P), TRAF2-KO, TRAF3-KO, and TRAF2/3-DKO lymphoma cells with DOX, AZD, or AZD plus DOX." (PMID 37679334, 2023). "The NFκB system in general affects a variety of cancer relevant processes, and it is thus not surprising that TRAF2 via its role in NFκB signaling not only contributes to malignant transformation of lymphoma but also to development of solid cancers." (PMID 36011046, 2022).
neuroblastoma (3 papers, 2016 to 2023). Neuroblastoma (NB) is the most common solid, extracranial childhood tumor. "Another study showing that IRE1 activates the TRAF2/JNK pathway in neuroblastoma cells confirmed the connection between ER stress and autophagy." (PMID 27275542, 2016). "High-glucose conditions induce a decreased expression of TRAF2 in neuroblastoma cells." (PMID 36927703, 2023). "In neuroblastoma, it has been shown to increase mitochondrial dysfunction and endoplasmic reticulum stress by stimulating caspases (caspase-3, 4, 8, 9, 12), PARP1, GRP-78/Bip, GRP-94/gp96, IRE1α, and TRAF2." (PMID 38249515, 2023).